INS (insulin)
Diseases named in the same sentence as INS in open-access papers (continued):
Sharing a sentence is not in itself a finding about the gene and the disease.
diabetes (continued). "It has also been suggested insulin dysfunction caused by obesity, diabetes, or cardiovascular disease might adversely influence brain neuronal functions." (PMID 32575897, 2020). "This scenario might cause progressive β-cell dysfunction, such as enhanced basal insulin secretion, which predispose to diabetes." (PMID 32934005, 2020). "Insulin resistance and/or insufficient insulin secretion are pathogenic mechanisms of diabetes." (PMID 32184820, 2020). "Third, high intakes of snack and chocolates with high glycaemic load could lead to an increase in weight gain, which can affect the metabolism of glucose and insulin sensitivity, thus increasing the risk of diabetes." (PMID 32731880, 2020). "The concept of how AD neurodegeneration could be linked to diabetes, deficits in insulin signaling and glucose metabolism, and endothelial dysfunction should be considered." (PMID 33302545, 2020). "The aim of this study was to clarify the effectiveness of the LCCP app-based diabetes education program for glycemic control among patients with diabetes treated with insulin and to understand the factors associated with patients’ engagement in diabetes education on the LCCP platform." (PMID 32141838, 2020). "Similarly, predictors of the risk of severe hypoglycemia in outpatients with diabetes included kidney disease, age, insulin use, sulfonylurea use, history of hypoglycemia, and history of emergency or hospitalization related to hypoglycemia." (PMID 33015194, 2020). "Studies have shown that humans with diabetes and animal models of type 1 and 2 diabetes have impairments in cognitive function, synaptic plasticity, synaptogenesis, neurogenesis, and cell death caused by diabetes-related oxidative stress and deficits in insulin signaling." (PMID 33050583, 2020). "It has been proven that insulin therapy may improve glycemic control and reduce the risk of long-term complications in persons with diabetes." (PMID 32626786, 2020). "Thus, the observation of glucose intolerance in mice and patients treated with simvastatin supports the view that statins decrease insulin sensitivity and thereby increase the risk for developing diabetes." (PMID 32942550, 2020). "Diabetes is associated with impaired insulin signaling in the brain." (PMID 32192190, 2020). "The current study results imply that HCV induced diabetes might have some cause other than serum iron metabolism (as proposed by previous literature such as reactive oxygen species induced by hepatitis C, insulin signaling defects, or steatosis)." (PMID 33520544, 2020). "Having appreciated the secretion of pancreatic hormones and the structural similarity compared to pancreatic islets, we intuitively asked if htNSCPGHM spheres could have a therapeutic effect against insulin-deficient diabetes." (PMID 32081132, 2020). "Furthermore, another study of 119 participants (61% were Black), reported that emotional burden of diabetes was caused by the prescription of insulin." (PMID 31549366, 2020). "Type 1 diabetes mellitus (T1D) is an insulin-dependent chronic metabolic disease that most often develops during childhood and is caused by autoimmune reaction leading to impaired insulin production." (PMID 33198375, 2020). "The association between TG and diabetes may be partly mediated by insulin resistance and increased insulin secretion." (PMID 33679598, 2020). "In a cross-sectional study including 420 individuals, both fasting serum insulin and C-peptide levels were associated with diabetes that increased progressively from individuals with normal glucose tolerance to impaired fasting glucose, impaired glucose tolerance and type 2 diabetes, respectively." (PMID 32957570, 2020). "Recent evidence suggests mutual underlying pathologies between diabetes mellitus and neurodegeneration due to the homeostatic imbalance of glucagon–insulin in diabetes mellitus, which induces amyloid deposition in the pancreatic islets of Langerhans’s and the brain." (PMID 32085610, 2020).
diabetes (continued). "In addition, a plethora of studies in rodent models of diabetes suggest that both glucose neurotoxicity and deficient insulin signaling impair brain structure and function leading to behavioral and cognitive alterations." (PMID 32265637, 2020). "Because our hypothalamic spheres impressively mimic the feature of pancreatic islets, we examined if they could provide a therapeutic effect against insulin-deficient diabetes." (PMID 32081132, 2020). "Indeed, in proteoglycans, GPC-4 is the first-identified adipokine that associates with diabetes via increasing insulin sensitivity." (PMID 32467736, 2020). "However, antagonizing aAb are also described, e.g., in type B insulin resistance, where aAb to the insulin receptor impairs insulin effects, causing a form of diabetes that is refractory to therapeutic insulin application." (PMID 31940750, 2020). "From a clinical perspective, the measurement of serum insulin concentration provides useful information for the diagnosis of insulin deficiency and insulin resistance, particularly in diabetes, neonatal hyperinsulinemia hypoglycemia, insulinoma, and polycystic ovary syndrome." (PMID 32506749, 2020). "Lipid accumulation in hepatocytes is highly prevalent in diabetes and could increase the diabetes risk through disordered lipid metabolism and transport, which may link the dysfunction of insulin to a metabolic disorder of the liver." (PMID 31790971, 2020). "In addition, hesperidin treatment in diabetes-induced rats inhibited weight loss, reduced insulin concentrations, normalized blood glucose, reduced food and water intake, increased SOD and GSH levels, and reduced MDA and NO levels." (PMID 32977511, 2020). "However, it is important to consider the increased insulin sensitivity caused by physical activity, both in amateurs and professional athletes with diabetes which continues even after exercise." (PMID 33467298, 2020). "As diabetes usually involves insulin deficiency, we hypothesized that P4-mediated gluconeogenesis might increase blood glucose when insulin action is limited." (PMID 33005004, 2020). "Paucity of muscle mass may be a determinant for diabetes in the future, as muscle is an important insulin target tissue and decreased muscle mass is linked to insulin resistance." (PMID 33182482, 2020). "According to the Japan Diabetes Society, a lower HbA1c limit is set for older patients with diabetes if they are prescribed a drug, such as insulin, an SU drug, or a glinide, which may cause severe hypoglycemia." (PMID 32206324, 2020). "Diabetes mellitus (DM) is an illness which mainly characterized by a high blood glucose level (hyperglycemia) with defects in carbohydrates, protein and fat metabolism due to either absolute or relative deficiency of insulin and/or action." (PMID 32699242, 2020). "Good metabolic control at 1 year was negatively associated with age, OR 0.96 (0.93–0.99), p = 0.003, diabetes duration, OR 0.93, (0.90–0.97), p < 0.0001, baseline treatment with insulin, OR 0.12 (0.03–0.43), p = 0.001 and baseline HbA1c, OR 0.71 (0.63–0.80), p < 0.001." (PMID 32283783, 2020). "Diabetes can be generally classified as type 1 diabetes (the inability to produce enough insulin due to loss of insulin-producing β-cells) and type 2 diabetes (non-response of peripheral tissues to insulin leading to impaired uptake of glucose from the bloodstream)." (PMID 32899334, 2020). "Alanine (Ala) is a gluconeogenic substrate linked to impaired insulin sensitivity prior to the elevation of fasting glucose or insulin levels and may predict the incidence of diabetes as a marker of attenuated glucose tolerance." (PMID 33319826, 2020). "Glucose-induced oxidative stress is associated with the overproduction of reactive oxygen species (ROS), which may dysregulate the expression of genes controlling insulin secretion leading to β-cell dysfunction, a hallmark of type 2 diabetes mellitus (T2DM)." (PMID 32392844, 2020).
diabetes (continued). "Although the majority of patients with diabetes and severe HTG have type 2 diabetes, severe HTG may occur in poorly controlled insulin deficient diabetes, where the combination of LPL deficiency and continued dietary fat intake are key factors." (PMID 33193106, 2020). "mtDNA content may be linked with type 2 diabetes mellitus and can serve as an indicator of insulin sensitivity." (PMID 31941967, 2020). "An increase in insulin level is associated with weight-gain in patients with diabetes, and a fall in insulin level may be a contributing factor to weight loss after bariatric surgery." (PMID 32314253, 2020). "However, hyperglycaemia in diabetes is mostly caused by defects in insulin secretion, insulin resistance, and functional disruptions of various organs (e.g., the brain, gut, and kidney)." (PMID 32724305, 2020). "However, Gray and colleagues, unlike the present report, employed a severe model of streptozotocin-induced insulin-deficient diabetes, which is more reminiscent of type 1 diabetes mellitus and itself leads to immune dysfunction." (PMID 32401607, 2020). "In our cohort, the low incidence of insulin-treated diabetes (GDM-2) may be associated with the exclusion of pre-existing diabetes, the low number of women with diabetes in early pregnancy, and the low incidence of obesity." (PMID 32599847, 2020). "In addition, an increasing number of studies are supporting a key role for this vitamin in improving lipid profile and insulin sensitivity and reducing the risk of type 2 diabetes mellitus, but little is known about what mechanisms would be involved." (PMID 32267358, 2020). "Diabetes is caused by insulin synthesis or secretion damage, which leads to hyperglycemia." (PMID 32312941, 2020). "However, concomitantly with beta cells hyperactivity, the pre-diabetes stage presents loss of the first-phase of insulin secretion and about 50% loss of beta cell number due to apoptosis." (PMID 32128655, 2020). "These patch-like devices are now included in the American Diabetes Association’s current clinical practice recommendations as an alternative to insulin pens and syringes, but prospective data evaluating the use of these devices in a real-world practice setting are limited." (PMID 31833010, 2020). "However, the mediating role of insulin use on the association between strength and glycaemic control in patients with diabetes would merit further investigation." (PMID 32183393, 2020). "A steady-state rise of cytosolic Ca2+ concentrations in stimulated β-cells could be responsible for the loss of the pulsatile insulin signals, a process occurring at the onset of diabetes." (PMID 31817135, 2019). "Changes in insulin structure, insulin receptors, obesity, and long-term hyperglycemia may all lead to insulin resistance and then increase the susceptibility of diabetes." (PMID 30621321, 2019). "Ectopic lipid storage strongly affects the extent of insulin sensitivity and may thus be a key characteristic explaining the link between greater height and lower diabetes risk." (PMID 31501920, 2019). "An adequate vitamin D level can also improve insulin resistance pathways associated with diabetes." (PMID 30884820, 2019). "Obesity-related diabetes is mainly associated with insulin resistance and/or hyperinsulinemia due to reduced number of insulin receptors, impaired insulin-receptor binding and disruption in post-receptor insulin signalling transduction." (PMID 31844729, 2019). "Similarly, deletion of Nkx6.1 in adult mice caused diabetes due to the reduction in insulin secretion and β-cell proliferation." (PMID 31300714, 2019). "Structured intensive diabetes education programs (SIDEPs) can motivate and empower patients to take control of their disease and have been associated with improved glycemic control, better weight management, and better adherence on insulin." (PMID 31576267, 2019).
diabetes (continued). "Diabetes mellitus (DM), generally referred to as diabetes, is an endocrine disorder with the symptom of persistent high blood glucose levels caused by the decrease or defect of insulin." (PMID 31888196, 2019). "However, it was also reported that the cardiac GLUT4 expression is decreased under insulin-resistant conditions, such as diabetes, in association with the reduction in glucose uptake, leading to impaired glucose utilization in the heart." (PMID 31262297, 2019). "Previous evidence has shown that DRT in rats with diabetes, middle-aged and obesity induced by a hyperlipidic diet, reduced pro-inflammatory markers, and was associated with improved insulin sensitivity in skeletal muscle." (PMID 30723416, 2019). "Associations between dopamine receptors and insulin levels have been described before, and antipsychotics, which block dopamine receptors, are linked with insulin resistance and diabetes in psychiatric patients." (PMID 31031804, 2019). "Thus we would anticipate that these clinical and genetic factors can be combined in risk prediction models to predict risk of diabetes progression (to failure of therapy or need for insulin) or risk of complications." (PMID 31161345, 2019). "Parameters of lipid metabolism in the blood, such as total glycerol (TG) and total cholesterol (TC), and diabetes-associated parameters, such as the levels of insulin and HbA1c, were found to be modulated in the DM animals, thereby showing the disruption of the metabolic homeostasis in DM mice." (PMID 30987324, 2019). "In a rodent model of uncontrolled insulin‐deficient diabetes, Meek and colleagues report that infusion of BDNF to either the lateral cerebral ventricle or the VMH attenuates diabetic hyperglycemia via an insulin‐independent inhibition of hepatic glucose production." (PMID 30585393, 2019). "Any interruption in the pathway of metabolism of glucose and lipids may cause glucotoxicity and lipotoxicity in diabetes which leads to impaired beta-cell functions, and increases insulin resistance in muscles, liver, and adipose tissue." (PMID 30944708, 2019). "Some researchers reported that snoring was associated with diabetes and insulin sensitivity, whereas other studies showed that although snoring was more common in men, it significantly increased the odds for diabetes or impaired glucose tolerance only in women." (PMID 31093507, 2019). "It is unclear whether pancreatic atrophy is accompanied by loss of insulin secretory function in patients with long-standing diabetes." (PMID 31467928, 2019). "Insulin is the mainstay drug in type 1 diabetes mellitus (T1D); however, the use of insulin is associated with haematological alterations that could further worsen cardiovascular complications." (PMID 31828165, 2019). "This study found that drinking increased insulin sensitivity and reduced the risk of diabetes." (PMID 30823556, 2019). "In an insulin-deficient mouse model of diabetes, astrocytes retract at the BBB." (PMID 31213970, 2019). "It has been proposed that increased insulin signaling might exert adverse effects on cardiac remodeling, vasculature, kidneys, and adipose tissue, thus predisposing an individual with diabetes to HF and HFpEF in particular." (PMID 31749710, 2019). "Any functional defect in GCK suppresses glucose utilization in the liver and decreases insulin secretion from β cells, which may cause diabetes." (PMID 31882596, 2019). "Patients with diabetes are at high risk for life threatening hypoglycemia due to insulin therapy or other drugs that increase insulin secretion, which may lower blood glucose below 60–70 mg/dl." (PMID 30503832, 2019). "Epidemiologic studies have found that elevated insulin levels and chronic hyperglycemia among breast cancer (BC) survivors are associated with poor prognosis; few of these studies have included Hispanic women in whom diabetes is highly prevalent." (PMID 30675513, 2019).
diabetes (continued). "It is one of the most important ways to effectively control diabetes, decrease insulin demand and reduce the risk of chronic complications, such as cardiovascular disease and hypertension, which show a 10-fold more frequent occurrence in patients with T1D compared to the healthy population." (PMID 31546871, 2019). "It is indicated that Cr takes part in insulin signalling and increases sensitivity to insulin of insulin-sensitive cells, and deficiency, rare as it is, increases the risk of metabolic diseases and diabetes." (PMID 30715682, 2019). "The new insulin analogues and oral diabetes medicines have been associated with high expenditures, both for individuals and governments and the cost of these medicines are considered a major challenge in accessing these medicines particularly in low- and middle-income countries (LMICs)." (PMID 31824316, 2019). "However, an important link of EGFR and diabetes has been identified before: elevated levels of ErbB2 are associated with hyperglycemia and impaired insulin sensitivity." (PMID 31815004, 2019). "Therefore, reducing the risk of insulin-induced hypoglycemic events is essential in the management of diabetes." (PMID 31397845, 2019). "Hyperglycemia is the hallmark of diabetes and is caused by impaired insulin synthesis or secretion." (PMID 31382473, 2019). "Both statins and PSCK9 inhibitors increase insulin resistance or reduce insulin release, which could increase the risk of diabetes in predisposed individuals." (PMID 30922303, 2019). "Diabetes per se may also induce urinary magnesium loss, caused by hyperglycemia, hyperfiltration or a direct effect of insulin on the kidneys’ magnesium Mg channels." (PMID 31604444, 2019). "Recently, it was shown that metformin may improve the prognosis that is associated with diabetes and insulin treatment, mainly in patients with primary HER2-positive and hormone receptor-positive breast cancer." (PMID 30989432, 2019). "However, this association was lost after controlling for gender, age, diabetes duration, hypertension, BMI, insulin use and renal function." (PMID 30467971, 2019). "Given the fact that obesity is commonly associated with insulin resistance and type 2 diabetes mellitus, we also examined the relationship between Mboat7 expression and insulin sensitivity in the HMDP." (PMID 31621579, 2019). "In a genetically obese model of diabetes (db−/db−) induced by leptin receptor deficiency, diabetic mice demonstrated a worse metabolic profile than lean controls, including elevated glucose, insulin, and triglycerides." (PMID 31382355, 2019). "This can eventually lead to low insulin sensitivity and increased risk of obesity and diabetes." (PMID 31903092, 2019). "Diabetes mellitus is a chronic disease caused by an absolute or relative deficiency of insulin." (PMID 30998218, 2019). "This implies that extending GH into older people may increase the problem of insulin insensitivity (causing more diabetes) and remove the low-GH protection effect from cancers and tumors." (PMID 31636602, 2019). "Insulin action on the microvasculature has been suggested to mediate protective effects against diabetes-associated vascular complications by stimulating Ca2+-independent NO production at the onset of insulin resistance that could be impaired later." (PMID 31333501, 2019). "As diabetic ketoacidosis only occurs in situations of severe insulin deficiency, this implies that antipsychotics reduce insulin secretion, either through a toxic effect on the pancreatic β cells or pharmacological action that disrupts normal insulin secretion." (PMID 31478094, 2019). "This observed muscle weakness implies that these animals are unable to perform adequate exercise, which in turn may also enhance insulin resistance and predispose them to develop diabetes." (PMID 31340612, 2019).